IL37 (interleukin 37)
Diseases named in the same sentence as IL37 in open-access papers (continued):
Sharing a sentence is not in itself a finding about the gene and the disease.
cyst (1 paper, 2026). A sac-like closed membranous structure that may be empty or contain fluid or amorphous material. "The interplay of pro-inflammatory and anti-inflammatory mediators in ADPKD highlights a complex immune environment, where cytokines like IL-1β, IL-6, and IL-37 play key roles in cyst formation and inflammation regulation." (PMID 41431718, 2026). "Recent findings suggested that IL37, an anti-inflammatory cytokine, has the potential to reduce cyst burden and inflammation in ADPKD." (PMID 41431718, 2026).
demyelinating disease of the CNS (1 paper, 2022). "However, in the transgenic homozygote of human IL-37 (hIL-37tg) mice lacking IL-1R8, the beneficial effects of IL-37 were completely absent in demyelinating disease of the CNS, indicating IL-37 acts with IL-1R8." (PMID 35741608, 2022).
demyelinating diseases of the (1 paper, 2021). "Since the role of IL-37 in demyelinating diseases of the CNS is still poorly understood, we first sought to explore whether this cytokine exerted beneficial effects in EAE mice." (PMID 33391457, 2021).
diabetic neuropathy (1 paper, 2023). A chronic, pathological complication associated with diabetes mellitus, where nerve damages are incurred due to diabetic microvascular injury involving small blood vessels that supply these nerves, resulting in peripheral and/or autonomic nerve dysfunction. "When IL‐37 and IL‐39 were classified according to age group, gender, BMI, family history, diabetic neuropathy, disease duration and FPG percentiles, only four significant differences were found." (PMID 36757903, 2023). "Classification of IL‐37 and IL‐39 levels by demographic and clinical characteristics of patients revealed some significant differences including gender (IL‐39), body mass index (BMI; IL‐37 and IL‐39) and diabetic neuropathy (IL‐39)." (PMID 36757903, 2023).
dysplasia (1 paper, 2021). A usually neoplastic transformation of the cell, associated with altered architectural tissue patterns. "However, IL-37 is less expressed in OLK patients without dysplasia than in those with mild/moderate dysplasia." (PMID 34248996, 2021).
endometrial carcinoma (1 paper, 2023). A malignant tumor arising from the epithelium that lines the cavity of the uterine body. "In the case of endometrial carcinoma, progesterone exertion was suspected to inhibit anti-inflammatory cytokines production, which was confirmed for IL-10 and excluded for IL-37." (PMID 36769226, 2023). "Moreover, the activity of NF-κB pathways may also decrease the expression of IL-37 protein in cancer cells, confirming the inhibitory roles of IL-37 on metastasis in endometrial carcinoma." (PMID 36769226, 2023). "In the case of endometrial carcinoma, estradiol action was suspected to inhibit IL-10, but not IL-37 anti-inflammatory cytokines production." (PMID 36769226, 2023).
endothelial dysfunction (1 paper, 2024). In vascular diseases, endothelial dysfunction is a systemic pathological state of the endothelium (the inner lining of blood vessels) and can be broadly defined as an imbalance between vasodilating and vasoconstricting substances produced by (or acting on) the endothelium. "Considering the protective role of IL-37 in endothelial cell apoptosis in an endothelial dysfunction model, IL-37 treatment significantly decreased the number of apoptotic cells in an in vitro model using human umbilical vein endothelial cells treated with oxidized low-density lipoprotein." (PMID 39335538, 2024).
enteritis (1 paper, 2022). Inflammation of the small intestine. "Mechanistically, the adverse effects of IL-37 in this mouse model are attributed to the intestinal barrier destruction causing intestinal microbiome dysbiosis, which leads to an uncontrollable enteritis incident by accumulating NK and neutrophils." (PMID 35836813, 2022).
epithelial dysplasia (1 paper, 2016). "We analyzed the relationship between IL-37 levels and the degree of epithelial dysplasia in patients with OLK through a tissue microarray (TMA)." (PMID 27225603, 2016). "Our results showed that IL-37 is dramatically overexpressed in OLK, and to gain further insight into IL-37 expression at different degrees of epithelial dysplasia in OLK, TMA was used." (PMID 27225603, 2016). "A positive relationship between IL-37 expression and epithelial dysplasia in OLK has been revealed." (PMID 27225603, 2016). "IL-37 immunoreactivity was detected clearly in OLK patients with both mild and moderate epithelial dysplasia, mainly in the keratin layer, spinous layer, and granular layer." (PMID 27225603, 2016). "This is the first time that IL-37 has been reported as a potential predictor for malignant potential in OLK patients, especially in patients with epithelial dysplasia." (PMID 27225603, 2016). "IL-37 was also detected in patients without epithelial dysplasia, but was much weaker than the other two groups." (PMID 27225603, 2016).
eumycetoma (1 paper, 2019). "In conclusion, this study indicates that both IL-35 and IL-37 are negatively associated with the levels of IL-1β and IL-12 in eumycetoma mycetoma infection; and high levels of IL-37 and IL-35 may have a negative impact on disease progression." (PMID 30946748, 2019). "Data of the current study clearly showed the serum levels of IL-1β and IL-12 in eumycetoma patients with different lesion size and disease duration were positively correlated with each other, and negatively correlated with IL-35 and IL-37." (PMID 30946748, 2019). "Our data showed that eumycetoma patients presented higher circulating levels of IL-1β, IL-12, IL-37 and IL-35 compared to controls." (PMID 30946748, 2019).
gastritis (1 paper, 2026). Inflammation of the stomach. "Collectively, our findings reveal that H. pylori induces production of the pan-immunosuppressive cytokine IL-37 to enhance colonization, modulate gastritis and suppress innate, cellular and humoral immunity to ultimately promote pathogenesis in the host." (PMID 41689434, 2026).
Granuloma (1 paper, 2022). A compact, organized collection of mature mononuclear phagocytes, which may be but is not necessarily accompanied by accessory features such as necrosis. "Although the group receiving CPP-IgG2Fc-IL-37 showed the greatest reduction in granuloma area, there was no statistical significance between the three IL-37 groups." (PMID 36002836, 2022). "Similarly, liver egg granuloma was significantly inhibited in the CPP-IgG2Fc-IL-37 and no CPP-IgG2Fc-IL-37 groups compared with the rIL-37 group." (PMID 36002836, 2022).
hemorrhagic stroke (1 paper, 2017). A stroke caused by a bleed on the brain. "IL-37 has yet to be evaluated in other non-immune neurological pathologies like ischemic or hemorrhagic strokes." (PMID 29234571, 2017). "IL-37 has yet to be evaluated in non-immune-mediated neurological diseases, such as ischemic or hemorrhagic strokes." (PMID 29234571, 2017).
hypothyroidism (1 paper, 2025). Abnormally low levels of thyroid hormone. "Hypothyroidism is closely associated with perturbation in IL-10 and IL-37." (PMID 40672362, 2025).
infarction (1 paper, 2025). A localised pathological necrosis of tissue resulting from obstruction of the blood supply usually by a thrombus, an embolus, or vascular torsion. "IL‐37 modulates the immune system by restoring a tolerogenic immune response, alleviating postmyocardial infarction remodeling." (PMID 41200280, 2025).
infertile (1 paper, 2023). "One study, published in 2017, reported SP IL37 concentration to be significantly higher in infertile men with varicocoele, compared to healthy fertile men." (PMID 36891953, 2023).
interstitial lung disease (1 paper, 2021). A diverse group of lung diseases that affect the lung parenchyma. "IL-37 has been reported to have a protective effect in interstitial lung disease through the inhibition of transforming growth factor-β1 signaling and the enhancement of fibroblast autophagy." (PMID 34086758, 2021).
IPEX syndrome (1 paper, 2023). "The remaining 13 patients have NOTCH1 mutation (n = 1); ALPS-Caspase10 (n = 1); CD137 deficiency (n = 1); interleukin-37 deficiency (n = 1); IPEX syndrome (n = 1); prolidase deficiency (n = 1); PRKCD deficiency (n = 1); MAGT1 deficiency (n = 1); and unspecified immune dysregulatory disease (n = 5)." (PMID 37559153, 2023).
ischemia reperfusion injury (1 paper, 2021). Adverse functional, metabolic, or structural changes in ischemic tissues resulting from the restoration of blood flow to the tissue (reperfusion), including swelling; hemorrhage; necrosis; and damage from free radicals. "IL-37 gene-modified MSCs (IL-37-MSCs) can distinctly inhibit intestinal ischemia reperfusion injury (IRI) by migrating to the damaged tissue." (PMID 34248996, 2021).
migraine (1 paper, 2019). "Therefore, the therapeutic anti-inflammatory value of IL-37 induced blocking of mast cells deserves further clarification in migraine research." (PMID 30795781, 2019).
neuropathy (1 paper, 2023). A disorder affecting the nervous system that manifests with pain, tingling, numbness, and/or muscle weakness. "T2DM patients with neuropathy in this study also showed elevated serum levels of IL‐37 compared to patients without neuropathy (82 vs. 76 ng/L) but the difference was no significant." (PMID 36757903, 2023).
oral cancers (1 paper, 2025). "IL-37 attenuates the proliferation of oral cancer cells induced by lipopolysaccharide and tumor necrosis factor-alpha, while knockdown of IL-37 exacerbates this induction." (PMID 40444012, 2025). "Mechanistically, it was revealed that STAT3 closely regulated inflammation in oral cancer cells, and the use of stattic significantly compromised the inhibitory effects of IL-37 on the growth of oral cancer cells and the promotive effects on apoptosis." (PMID 40444012, 2025). "The results revealed that IL-37 significantly curtailed cell viability while promoting apoptosis in oral cancer cells." (PMID 40444012, 2025). "This study observed that the STAT3 inhibitor stattic robustly compromised TNF-α-induced upregulation of inflammation-related genes in oral cancer cells, emphasizing the significant role of IL-37 in modulating inflammation in these cells." (PMID 40444012, 2025). "Our findings reveal that IL-37 markedly inhibits cell viability and induces apoptosis in oral cancer cells." (PMID 40444012, 2025). "In the present study, IL-37 demonstrated significant effects on oral cancer cells, including a decrease in cell viability and an increase in apoptosis, while IL-37 has minor effect of growth normal oral cell line." (PMID 40444012, 2025). "Collectively, these findings demonstrate that IL-37 regulates the growth, proliferation, and apoptosis of oral cancer cells via STAT3." (PMID 40444012, 2025). "In further investigating the mechanism by which IL-37 regulates the activities of oral cancer, oral cancer cells were co-treated with IL-37 and stattic." (PMID 40444012, 2025). "In summary, these findings demonstrate that IL-37 effectively inhibits growth and promotes apoptosis in oral cancer cells." (PMID 40444012, 2025). "In this study, IL-37 was observed to significantly reduce the cell viability of oral cancer cells and induce apoptosis." (PMID 40444012, 2025). "Further investigation into the effects of IL-37 on the growth of oral cancer cells revealed that co-treatment of LPS and IL-37 resulted in a significant alleviation of the LPS-induced increase in cell viability for both HN13 and HSC-4 cells." (PMID 40444012, 2025). "Accumulating evidence points to the intricate role of IL-37 in regulating the pathogenesis of oral cancers." (PMID 40444012, 2025). "In summary, this study delved into the impact of IL-37 on inflammation, proliferation, apoptosis, and migration in oral cancer cells." (PMID 40444012, 2025). "IL-37 was also identified to have an inhibitory effect on inflammation in oral cancer cells." (PMID 40444012, 2025). "In summary, these findings indicate that IL-37 inhibits inflammation in oral cancer cells." (PMID 40444012, 2025). "Additionally, to verify the effects of IL-37 on the migration of oral cancer cells, a transwell migration experiment was conducted." (PMID 40444012, 2025). "IL-37 demonstrated a suppressive effect on inflammation in oral cancer cells." (PMID 40444012, 2025). "The KD of IL-37 further exacerbated LPS and TNF-α-induced proliferation of oral cancer cells, suggesting that IL-37 may play a crucial role in the activities of various cancer types, including oral cancer." (PMID 40444012, 2025). "This prompted an investigation into the impact of IL-37 on inflammation in oral cancer cells." (PMID 40444012, 2025). "The research delved into the intricate mechanisms through which IL-37 regulates oral cancers." (PMID 40444012, 2025). "Similarly, this study found that the STAT3 inhibitor stattic further promoted LPS- and TNF-α-induced increases in cell viability and migration of oral cancer cells, highlighting the crucial role of IL-37 in regulating the growth, proliferation, and migration of oral cancer cells." (PMID 40444012, 2025). "Furthermore, IL-37 demonstrates anti-inflammatory effects on oral cancer cells." (PMID 40444012, 2025). "The results revealed that IL-37 (100 nM) significantly increased apoptosis in both HN13 and HSC-4 oral cancer cells." (PMID 40444012, 2025).
oral cancers (continued). "Collectively, these findings demonstrate that IL-37 effectively mitigates the proliferation and migration induced by LPS and TNF-α in oral cancer cells." (PMID 40444012, 2025). "The study employed two oral cancer cell lines, namely HN13 and HSC-6, to systematically investigate the impact of IL-37 on the proliferation and apoptosis of oral cancer cells." (PMID 40444012, 2025). "Collectively, these findings demonstrate that KD of IL-37 exacerbates the LPS- and TNF-α-induced proliferation and migration of oral cancer cells." (PMID 40444012, 2025). "Moreover, IL-37 mitigated the proliferation induced by LPS and TNF-α, and the KD of IL-37 exacerbated the proliferation triggered by LPS and TNF-α in oral cancer cells." (PMID 40444012, 2025). "Furthermore, IL-37 mitigated the proliferation of oral cancer cells induced by LPS and TNF-α, while the KD of IL-37 exacerbated this proliferation." (PMID 40444012, 2025). "Moreover, IL-37 mitigated LPS and TNF-α-induced proliferation and migration of oral cancer cells." (PMID 40444012, 2025).
oral diseases (1 paper, 2016). "To investigate the expression of IL-37 in oral diseases, we performed immunohistochemistry on local-pathologically-changed tissues from individuals with OLK and OSCC." (PMID 27225603, 2016).
pancreatic ductal adenocarcinoma (1 paper, 2020). An infiltrating adenocarcinoma that arises from the epithelial cells of the pancreas. "However, the biological functions and the exact molecular mechanisms of IL-37 in pancreatic ductal adenocarcinoma (PDAC) development and chemo-resistance are yet to be examined." (PMID 32226541, 2020).
peritonitis (1 paper, 2016). Inflammation of the peritoneum (tissue that lines the abdominal wall and covers most of the organs in the abdomen). "We then assessed the impact of IL-37 on an MSU-crystal-induced mouse peritonitis model." (PMID 27863506, 2016).
primary progressive MS (1 paper, 2019). "None of the patients with primary progressive MS (PP-MS) had detectable IL37 in sera." (PMID 31861585, 2019).
pyoderma gangrenosum (1 paper, 2025). An idiopathic, rapidly evolving, and severely debilitating disease occurring most commonly in association with chronic ulcerative colitis. "Our findings reveal a dysregulated IL-36 cytokine profile in pyoderma gangrenosum, marked by reduced serum levels of IL-36α and IL-36γ and elevated levels of IL-36Ra, IL-37, and IL-38." (PMID 41465501, 2025). "Future studies should aim to validate this hypothesis by assessing the active forms of IL-36, IL-37, and IL-38 both in serum and, crucially, within lesional tissue, to better characterize their local biological activity in pyoderma gangrenosum." (PMID 41465501, 2025).
respiratory infections (1 paper, 2014). "The ability to limit inflammatory cell recruitment was also observed in response to LPS, a finding consistent with the ability of IL-37 to reduce LPS-induced pro-inflammatory cytokine expression and further pointing to a protective effect for IL-37 in respiratory infections." (PMID 25375146, 2014).
rhinitis (1 paper, 2021). An inflammation of the mucous membrane lining the nose, usually associated with nasal discharge. "IL-37 was also found to be negatively correlated with FeNO, ACT-score, atopy and rhinitis history in asthmatic adults." (PMID 34516405, 2021). "The obtained results revealed that IL-37 expression was negatively correlated with FeNO, ACT-score, atopy and rhinitis history." (PMID 34516405, 2021).
schistosomiasis (1 paper, 2022). An infectious disease caused by parasitic trematodes of the genus Schistosoma that colonize human blood vessels and release eggs that can cause granulomatous reactions leading to acute (swimmer's itch or acute schistosomiasis syndrome) or chronic disease. "Serum IL-37 levels were upregulated in schistosomiasis patients, and this increased level of IL-37 protein apparently alleviated the liver granuloma of mice in infection models." (PMID 36002836, 2022). "To investigate the potential role of IL-37 in patients with schistosomiasis, we recruited 14 acute patients with schistosomiasis and 14 age- and gender-matched healthy controls into this study." (PMID 36002836, 2022). "The results show that IL-37 was able to promote the polarization of macrophages to the M2 phenotype, thereby inhibiting the development of schistosomiasis." (PMID 36002836, 2022). "It has been reported that IL-37 can switch the polarization of macrophages from a pro-inflammatory M1 phenotype to a beneficial anti-inflammatory M2 phenotype in temporomandibular joint inflammation, but this mechanism of IL-37 in schistosomiasis has not yet been studied." (PMID 36002836, 2022).
secondary progressive MS (1 paper, 2019). "In particular, IL37 could be detected in 1 clinically isolated syndrome (CIS) patient (concentration: 616.953 pg/mL) in 8 out of the 95 RR-MS patients (one sample was lost due to technical reasons) and in 2 out of 8 secondary progressive MS (SP-MS) patients." (PMID 31861585, 2019).
Streptococcus pneumoniae infection (1 paper, 2025). "However, this anti-inflammatory property of IL-37 may, to a certain extent, weaken the ability of mice to control pneumococcal infection in the lungs." (PMID 41293155, 2025). "This altered immune response led to the development of necrotic pneumonia and increased mortality, revealing that the anti-inflammatory properties of IL-37 may, to some extent, weaken the mice’s ability to control Streptococcus pneumoniae infection in the lungs." (PMID 41293155, 2025). "In a mouse transgenic model expressing human IL-37b (IL-37tg), researchers observed that IL-37 reduced the expression of cytokines IL-6, TNF-α, and IL-1β during the early stages of Streptococcus pneumoniae infection." (PMID 41293155, 2025).
T-cell leukemia (1 paper, 2022). A malignant disease of the T-lymphocytes in the bone marrow, thymus, and/or blood. "On the other hand, IL-37 expression was minimal or undetectable in the non-Treg CD4+ T cell leukemia cell line, Jurkat cells, prompting us to use Jurkat cells to study biological changes after IL-37 overexpression." (PMID 36010641, 2022). "We then stably transfected the non-Treg CD4+ T cell leukemia cell line, E6 Jurkat cells, with IL37 and found significant induction of the Treg phenotype." (PMID 36010641, 2022). "We transduced the non-Treg CD4+ T cell leukemia cell line, E6 Jurkat cells, with lentivirus made from an IL37 overexpressing vector (IL37 OE) and demonstrated the induction of Treg-like phenotype and function in IL37 OE Jurkat cells, compatible to human primary Treg cells." (PMID 36010641, 2022).